CLDN6 (claudin 6)
Diseases named in the same sentence as CLDN6 in open-access papers (continued):
Sharing a sentence is not in itself a finding about the gene and the disease.
breast carcinoma (continued). "Our previous study reported that a low level of CLDN6 in breast cancer was due to DNA methylation, but the reason for low CLDN6 expression in breast cancer warrants further study." (PMID 35008557, 2021). "Our findings contribute to the understanding of the important role of CLDN6 in regulating breast cancer metabolism, especially aerobic glycolysis." (PMID 35008557, 2021). "First, we verified that CLDN6 was lowly expressed in breast cancer tissues and that patients with lower CLDN6 expression had a worse prognosis." (PMID 35008557, 2021). "In MCF-7 breast cancer cells, CLDN6 overexpression inhibits proliferation and anchorage-independent growth and induces apoptosis via ASK1-P38/JNK signaling in MCF-7 cells." (PMID 34948213, 2021). "In summary, these results suggested that the inhibitory effect of CLDN6 on breast cancer growth was c–MYC–dependent." (PMID 35008557, 2021). "Claudin 6 (CLDN6) was found to be a breast cancer suppressor gene, which is lowly expressed in breast cancer and inhibits breast cancer cell proliferation upon overexpression." (PMID 35008557, 2021). "Next, we confirmed that CLDN6 inhibited breast cancer proliferation through in vitro and in vivo experiments." (PMID 35008557, 2021). "Here, we investigated this issue and elucidated the molecular mechanisms by which CLDN6 inhibits breast cancer proliferation." (PMID 35008557, 2021). "CLDN6, one of 28 members of the CLDNs family 15, was first found and confirmed as a breast cancer suppressor gene." (PMID 34405008, 2021). "They subsequently demonstrated that the inhibitory effect of ERβ on breast cancer metastasis was dependent on CLDN6-mediated autophagy." (PMID 34948213, 2021). "In breast cancer, higher CLDN6 expression is significantly related to a longer OS and disease-free survival (DFS) of patients analyzed by the Kaplan–Meier plotter." (PMID 34948213, 2021). "Glycolysis, glycolytic capacity, and glycolytic reserve were found decreased upon CLDN6 overexpression in breast cancer cells by measuring ECAR." (PMID 35008557, 2021). "In MDA-MB-231 breast cancer cells, CLDN6 binds to another PDZ-containing protein AF-6 to inhibit its downstream ERK activation." (PMID 34948213, 2021). "Studies have shown that CLDN6 inhibits the development and progression in some cancers such as breast cancer, cervical cancer, and meningioma." (PMID 34948213, 2021). "CLDN6 expression is increased in multidrug-resistant breast cancer cells and the relationship between CLDN6 and drug resistance will be discussed in Section 5.2.3." (PMID 34948213, 2021). "In this study, we focused on the expression and prognosis of CLDN6 in breast cancer patients and explored the mechanism by which CLDN6 inhibited breast cancer proliferation." (PMID 35008557, 2021). "CLDN6 has the possibility to be used as a biomarker for the diagnosis and prognosis of breast cancer." (PMID 35008557, 2021). "A recent study indicated that in breast cancer cell lines, ER-β inhibited migration through CLDN-6-mediated autophagy." (PMID 35011656, 2021). "Consistently, the overexpression of SENP1 or HIF-1α significantly restored the CLDN6-mediated reductions in circulating tumour cells, indicating that CLDN6 inhibits breast cancer metastasis through SENP1/HIF-1α signalling in vivo." (PMID 32093760, 2020). "In summary, this study provides new evidence for the clinical and biological significance of CLDN6 in breast cancer." (PMID 32093760, 2020). "In this study, we aim to explain this confusing finding and delineate the role of CLDN6 in the breast cancer metastasis induced by hypoxia." (PMID 32093760, 2020). "The CLDN6-overexpressing breast cancer cell lines had significantly weaker migratory and invasive abilities both in vitro and in vivo." (PMID 32093760, 2020). "We first detected HIF-1α expression in CLDN6-overexpressing breast cancer cells and found that CLDN6 significantly decreased HIF-1α accumulation under hypoxia." (PMID 32093760, 2020).
breast carcinoma (continued). "A decrease in SENP1 was also found in CLDN6-overexpressing breast cancer cell lines at both the mRNA and protein levels." (PMID 32093760, 2020). "Using lentivirus transduction, we constructed a breast cancer MDA-MB-231 cell line with stable overexpression of CLDN6." (PMID 32093760, 2020). "Due to the differences in breast cancer cell lines with different molecular subtypes, three breast cancer cell lines were used to detect CLDN6 expression under hypoxia (MDA-MB-231: basal-like; MCF-7: luminal A; and SkBr-3: HER2+)." (PMID 32093760, 2020). "We report for the first time, to our knowledge, that the inhibitory effects of ERβ on migration and invasion are mediated by CLDN6 and that CLDN6 is a target gene of ERβ in breast cancer." (PMID 31412908, 2019). "In this study, we demonstrated a novel finding that ERβ induced autophagy and inhibited migration and invasion via CLDN6 in breast cancer cells." (PMID 31412908, 2019). "We have reported that CLDN6 expression induces apoptosis and inhibits tumor growth, migration and invasion in breast cancer cells." (PMID 31412908, 2019). "To evaluate a potential functional link between E2 and CLDN6 in breast cancer cells, we treated MCF-7 (ERα+/ERβ+/GPR30+) and MDA-MB-231 (ERα−/ERβ+/GPR30-) cells with DMSO or E2 (from 5 nM to 100 nM) for 24 h." (PMID 31412908, 2019). "A series of subsequent experiments demonstrated that CLDN6 induced autophagy, whereas the relationship between CLDN6-induced autophagy and breast cancer remains poorly investigated." (PMID 31412908, 2019). "Western blot analysis and IF and acridine orange (AO) staining methods demonstrated that CLDN6 induced autophagy in breast cancer cells." (PMID 31412908, 2019). "Beclin1 knockdown reversed CLDN6-induced autophagy and the inhibitory effect of CLDN6 on breast cancer metastasis." (PMID 31412908, 2019). "Intriguingly, in this study, we found that ERβ induced autophagy and inhibited migration and invasion through claudin-6 (CLDN6) in breast cancer cells." (PMID 31412908, 2019). "Polymerase chain reaction (PCR) and western blot were used to characterize the effect of E2 on the expression of CLDN6 in breast cancer cells." (PMID 31412908, 2019). "CLDN6 overexpression suppressed the migration and invasion of breast cancer cells by reversing epithelial-mesenchymal transition (EMT)." (PMID 31412908, 2019). "Our data demonstrated that, in breast cancer cells, the low expression of CLDN6 was regulated by DNMT1 mediated methylation, which was in turn regulated by the SMAD2 pathway." (PMID 28867761, 2017). "We previously showed that CLDN6 was significantly downregulated in human breast cancer tissues compared to the adjacent tissues, and CLDN6 expression was relatively low in breast cancer cell lines MCF-7 and MDAMB231." (PMID 29116019, 2017). "CLDN6 is therefore suggested to function as a tumor suppressor by inhibiting malignant phenotype of breast cancer cells through various signaling pathways such as p38-MAPK, JAKs-STATs, ASK1-JNK, and other pathways." (PMID 29116019, 2017). "In this study, we investigated the role of CLDN6 in the acquisition of chemoresistance in breast cancer cells." (PMID 29116019, 2017). "We also found that, compared to immortalized breast epithelial cell line HBL-100, SMAD2 showed a higher expression in breast cancer cells, whereas CLDN6 had a lower expression level in these cells." (PMID 28867761, 2017). "In previous studies, we demonstrated that CLDN6 mitigated the malignant phenotype of MCF-7 breast cancer cells, and the expression of CLDN6 was undetectable or at low levels in human breast cancer cells." (PMID 28867761, 2017).
breast carcinoma (continued). "In the current study, we investigated the effects of CLDN6 expression in response to various anti-cancer drugs in breast cancer, and explore the role of GSTP1 in CLDN6 mediated chemoresistance in human breast cancer cells." (PMID 29116019, 2017). "In the current study, we aimed to explore the mechanism by which upstream signaling downregulates CLDN6 during mammary cancer progression." (PMID 28867761, 2017). "We cloned and identified the claudin-6 (CLDN6) gene, one of 27 members in the CLDN family, low levels of CLDN6 expression was observed in both human and rat mammary cancer." (PMID 29116019, 2017). "Here we show the mechanism by which DNA methylation regulates CLDN6 expression in human breast cancer cell line MCF-7." (PMID 27461117, 2016). "To further elucidate the mechanism of regulating CLDN6 methylation in breast cancer cells, we performed ChIP assay in MCF-7 cells treated with 5-aza-dC." (PMID 27461117, 2016). "RT-PCR, Western blot and immunofluorescent staining were utilized to investigate CLDN6 expression in breast cancer tissues and MCF-7 cells." (PMID 27461117, 2016). "Claudin-6 (CLDN6), a member of claudin transmembrane protein family, has recently been reported to be undetectable or at low levels in human breast cancer cell lines and tissues and plays a role in suppression of migration and invasion in breast cancer cells." (PMID 27461117, 2016). "The CLDN6 protein level was higher in breast pericarcinomatous tissues compared to breast cancer tissues." (PMID 27461117, 2016). "In the present study, the expression of CLDN6 was undetectable or at low levels in human and rat mammary cancer cell lines and tissues." (PMID 27461117, 2016). "We demonstrate that claudin-4 or claudin-6 blocking antibodies have different effects on VM formation in aggressive breast cancer cells in vitro." (PMID 25871476, 2015). "Specific inhibition of claudin-4 using mAbs led to complete inhibition of vascular channel formation in aggressive breast cancer cells, while this effect was minimal using claudin-6 blocking antibody." (PMID 25871476, 2015). "Epigenetic silencing of claudin-6 promoted anchorage-independent growth, cellular invasiveness and transendothelial migration of breast carcinoma cells, accompanied by an increase in matrix metalloproteinase activity." (PMID 23919729, 2013). "One study showed that decreased expression of claudin-6 enhances anchorage-independent growth and promotes cellular invasiveness of breast cancer cells." (PMID 24009024, 2013). "We found previously that, claudin-6 was down-regulated in breast cancer cells as well as in gastric cancer, but up-regulated in ovarian cancer cells." (PMID 24245968, 2013). "In another study, claudin-6 expression was associated with decreased anchorage-independent growth, invasion, and increased TER in breast carcinoma cells, suggesting a possible tumor suppressive role for claudin-6 in breast cancer." (PMID 24009024, 2013). "We cloned putative mammary cancer suppressor (mes) gene claudin-6 in mammary epithelial cells purified from Cop rat that extremely resistant to mammary cancer reduced by a variety of carcinogen." (PMID 23919729, 2013). "In our previous study, we found that claudin-6 is preferentially expressed in mammary epithelial cells and functions as a potential breast cancer suppressor gene, which is supported by the follow-up study of Osanai." (PMID 22925655, 2012). "Recently, we have discovered that the low level expression of claudin-6 gene contributed to malignant progression of breast cancer." (PMID 22925655, 2012). "In the previous study, We found that the expression level of claudin-6 was lower in two human breast cancer cells (MCF-7 and BT474) and one breast cancer sample than that in normal breast tissues." (PMID 22925655, 2012).
breast carcinoma (continued). "Claudin-6 is a candidate tumor suppressor gene in breast cancer, and has been shown to be regulated by DNA methylation and histone modification in breast cancer lines." (PMID 22455563, 2012). "Previous studies have demonstrated that claudin-6 functions as a cancer suppressor in human MCF-7 breast cancer cells." (PMID 22925655, 2012). "We have previously identified CLDN6 as a pivotal tumor suppressor in breast cancer." (PMID 39984471, 2025). "Collectively, these results suggest that CLDN6 promotes chemoresistance in breast cancer." (PMID 40959289, 2025). "We have previously shown that CLDN6 promoted the rearrangement of actin in breast cancer cells." (PMID 39984471, 2025). "A TMA exhibited low expression of CLDN6 in breast cancer compared to para-carcinoma tissues." (PMID 39984471, 2025). "To investigate whether CLDN6 promotes chemoresistance in breast cancer cells through protective autophagy, we treated MCF-7/CLDN6 and MDA-MB-231/CLDN6 cells with the autophagy inhibitor CQ." (PMID 40959289, 2025). "However, loss of CLDN6 disrupts this regulation and enhances HIF-1α-driven metastatic potential in a SUMOylation-dependent manner, further implicating CLDN6 in the control of breast cancer dissemination." (PMID 40687428, 2025). "In conclusion, this study opens up new possibilities for CLDN6 integrated with ferroptosis to predict the prognosis and reveals novel insights into the mechanism by which CLDN6 activates the ferroptosis process in breast cancer." (PMID 39984471, 2025). "Our results suggest that CLDN6 plays a pivotal role in breast cancer chemoresistance through protective autophagy, highlighting its potential as a therapeutic target to improve treatment outcomes of breast cancer patients." (PMID 40959289, 2025). "Claudin-6 (CLDN6) has been shown to be downregulated in breast carcinoma." (PMID 38540693, 2024). "In breast cancer, CLDN6 expression is driven by ERβ in a ligand-dependent manner." (PMID 38731853, 2024). "Moreover, CLDN6 was found to have an inhibitory function in breast cancer metastasis by upregulating WIP expression (WIP regulates the actin cytoskeleton autophagy pathways) during in vivo and vitro studies." (PMID 38731853, 2024). "Similarly, estrogen receptor beta has been shown to suppress breast cancer cell migration and invasion through CLDN6-mediated autophagy." (PMID 39629073, 2024). "In summary, we found that CLDN6 inhibited breast cancer metastasis via autophagy in vitro and vivo." (PMID 36935496, 2023). "In previous mRNA microarray, we observed that differential genes enriched in regulation of actin cytoskeleton in CLDN6-overexpressing breast cancer cells, which indicated that CLDN6 may mediate autophagy by affecting actin cytoskeleton." (PMID 36935496, 2023). "The critical role of WIP in CLDN6-mediated autophagy led us to hypothesize that CLDN6 may inhibit breast cancer metastasis by upregulating WIP expression." (PMID 36935496, 2023). "We demonstrated that CLDN6 inhibited breast cancer metastasis through autophagy in vitro and vivo." (PMID 36935496, 2023). "Finally, we found that CLDN6, WIP and LC3 expression correlated with each other, and WIP expression was significantly associated with lymph node metastasis of breast cancer patients." (PMID 36935496, 2023). "As a breast cancer suppressor gene, CLDN6 overexpression was found to inhibit breast cancer metastasis in our previous studies, but the specific mechanism remains unclear." (PMID 36935496, 2023). "This study aimed to clarify the role and mechanism of CLDN6 in inhibiting breast cancer metastasis." (PMID 36935496, 2023). "Given the heterogeneity of breast cancer and the fact that cancer treatment may require long-term administration of certain autophagy modulators, CLDN6 may act as a biomarker to monitor the autophagy status in vivo." (PMID 36935496, 2023).
breast carcinoma (continued). "We proved that CLDN6 was low expressed in breast cancer and CLDN6 overexpression suppressed breast cancer metastasis, but the underlying mechanism is not well understood." (PMID 36935496, 2023). "However, the role and relevant mechanism of CLDN6-mediated autophagy in regulating breast cancer metastasis needs to be explored." (PMID 36935496, 2023). "Autophagy inhibition by Beclin1 silencing inhibits Notch1 degradation, increases breast cancer cell migration and ERβ (known to act as a tumor suppressor in breast cancer), transactivates claudin-6 (CLDN6), and induces CLDN6-related autophagy to suppress migration and invasion in breast cancer." (PMID 36831154, 2023). "Wound healing and transwell migration and invasion assay revealed that WIP knockdown increased cell migration and invasion in CLDN6-overexpression breast cancer cells, which indicated that CLDN6 inhibited migration and invasion of breast cancer cells through WIP." (PMID 36935496, 2023). "However, increasing evidence showed that beside the membrane, CLDN6 was weakly expressed in the cytoplasm of different cells such as breast cancer tissues and adjacent tissues and atypical teratoid/rhabdoid tumors." (PMID 36362009, 2022). "Claudin-6 has been proposed as a tumor suppressor gene in breast cancer." (PMID 36430456, 2022). "Overall, DNA methylation is a well-explored regulator of CLDN6 expression in breast cancer cells, but whether this regulation is universal requires further investigation." (PMID 34948213, 2021). "We have reported that CLDN6 overexpression suppressed breast cancer metastasis by inhibiting EMT." (PMID 35008557, 2021). "Additionally, CLDN6 can interact with proteins containing PDZ domains or PDZ–binding motifs (PBMs) such as ZO–1, AF–6, and β–catenin through its PBM, which made CLDN6 communicate with proteins or pathways to play important roles in breast cancers." (PMID 35008557, 2021). "CLDN6 overexpression inhibited aerobic glycolysis in breast cancer cells." (PMID 35008557, 2021). "This important finding suggested that CLDN6 may be a suppressor gene in breast cancer and has stimulated a surge of research on the roles of CLDN6 in different cancers." (PMID 34948213, 2021). "The methylation mechanism of CLDN6 has been studied mainly in breast cancer cells." (PMID 34948213, 2021). "CLDN6 had been demonstrated abnormal expression and can be a prognostic marker in cancers including ovarian cancer, endometrial cancer, gastric cancer, breast carcinoma, and lung cancer." (PMID 34249076, 2021). "In light of former data, we further investigated the role of CLDN6 in breast cancer cells." (PMID 35008557, 2021). "CLDN6 inhibited the proliferation of breast cancer cells in vitro and in vivo." (PMID 35008557, 2021). "Previously, we found that CLDN6 suppress EMT in breast cancer cells." (PMID 34405008, 2021). "In breast cancers with low CLDN6 expression, CLDN6 overexpression inhibits tumor cell migration and invasion, while in cancers such as hepatocellular cancer with high CLDN6 expression, CLDN6 acts as a promoter of migration and invasion." (PMID 34948213, 2021). "Therefore, our data only provide a possible mechanism to explain the role of CLDN6 in hypoxia-induced breast cancer metastasis, and it is still necessary to explore further." (PMID 32093760, 2020). "We found that CLDN6 was transcriptionally upregulated by HIF-1α in three breast cancer cell lines." (PMID 32093760, 2020). "Accordingly, CLDN6 has been described as the tumour suppressor gene in breast cancer." (PMID 32093760, 2020). "Because CLDN6 attenuates hypoxia-induced tumour metastasis in a SUMOylation-dependent manner, these findings might provide a novel strategy for breast cancer treatment, and directly targeting SENP1/HIF-1α might prove to be a beneficial anti-cancer therapy." (PMID 32093760, 2020). "However, the inhibited metastasis was rescued by restoring HIF-1α in the CLDN6-overexpressing breast cancer cell lines." (PMID 32093760, 2020).